CXCL1 (C-X-C motif chemokine ligand 1)
Diseases named in the same sentence as CXCL1 in open-access papers (continued):
Sharing a sentence is not in itself a finding about the gene and the disease.
melanoma (continued). "One of the first names given to CXCL1 was derived from this effect: MGSA—melanoma growth-stimulatory activity." (PMID 38673949, 2024). "The chemotherapeutic agent paclitaxel has been found to elevate CXCL1 expression in malignant melanoma cells." (PMID 38673949, 2024). "With that said, there is more work needed on the effect of CXCL1 on the proliferation of malignant melanoma cells." (PMID 38673949, 2024). "CXCL1 is also known as melanoma growth-stimulating activity alpha (MGSA-α) and GRO-α in humans and as KC in mice." (PMID 38534751, 2024). "Recent extensive research has showed the participation of CXCL1 in various tumorigenesis processes, including lung cancer, melanoma, reproductive cancers, and gastrointestinal cancers." (PMID 39582536, 2024). "The important action of CXCL1 in tumorigenic processes in malignant melanoma allows the development of anticancer drugs." (PMID 38673949, 2024). "Intriguingly, while CXCL2 was expressed by fibroblasts from all skin cancer types, melanoma-derived CAFs expressed high levels of CXCL1-3, 5, 6 and 8 and IL1B as well as IL6, whereas the expression of CXCL9-11 and 13 was high in non-melanoma CAFs." (PMID 39516494, 2024). "At the same time, CXCL1 expression is higher in primary malignant melanoma than in metastatic malignant melanoma." (PMID 38673949, 2024). "CXCL1 expression in malignant melanoma cells is also dependent on CXCL1 itself inducing CXCR2 activation, which results in increased NF-κB activity in a mechanism dependent on Ras and p38 MAPK, which thus increases CXCL1 expression." (PMID 38673949, 2024). "CXCL1 has also been shown to promote the progression of tumors and participate in the angiogenesis of colon cancer and melanoma." (PMID 37940972, 2023). "Further, CXCL1 has been shown to constitutively increase expression of NF‐κB in melanoma which contribute to melanoma progression via angiogenesis." (PMID 37759347, 2023). "Large quantities of CXCL8/IL-8 and CXCL1/Groα were constitutively released in melanoma CM (~ 8 ng/ml and ~ 2 ng/mL, respectively)." (PMID 37525065, 2023). "TNF-α secreted by macrophages stimulated CXCL1 production in melanoma cells to facilitate tumor growth and metastasis." (PMID 36552865, 2022). "This was first performed by Kershaw and colleagues using the chemokine receptor CXCR2 to improve migration towards CXCL1-secreting human melanoma cell lines in 2002." (PMID 36366354, 2022). "Neutrophils of the tumour inflammatory infiltrate increase during melanoma progression, their accumulation depending on CXCL1, CXCL2, CXCL3, CXCL5, and CXCL8 molecules, which are stimulated by UV radiations." (PMID 35334544, 2022). "CXCL1 was first described in the 1980s as an auto-stimulatory melanoma mitogen, to which it owes one of its first names: melanoma growth-stimulatory activity (MGSA)." (PMID 35054978, 2022). "In melanoma, a pro-inflammatory phenotype is induced in astrocytes exposed to melanoma exosomes that included the upregulation of IL-1α, IL-1β, CXCL1 and CCL2 among others." (PMID 36704194, 2022). "CXCL1 was often referred to as an autostimulatory melanoma mitogen, and hence one of its first names, melanoma growth-stimulatory activity (MGSA)." (PMID 35457023, 2022). "During the 1980s CXCL1 was initially identified and isolated from culture supernatants of human melanoma Hs0294 T cells, and the CXCL1 gene was located on chromosome 4 (region q13→q21)." (PMID 35954156, 2022). "TNF-α secreted from macrophages induced the release of the C-X-C motif chemokine ligand 1 (CXCL1) from melanoma and lung carcinoma cells in a paracrine manner." (PMID 36552865, 2022). "To evaluate the importance of CXCL1 in the recruitment of immunosuppressive cells in human setting in relation to the clinical outcome, we analyzed TCGA data of 458 melanoma patients." (PMID 33578808, 2021). "For example, malignant melanomas express higher levels of CXCL1, CXCL2, and CXCL8 and receptors CXCR1, CXCR4, CCR10, and CCR7 compared with benign naevi." (PMID 34830780, 2021).
melanoma (continued). "CXCL1 was previously named GRO1 oncogene, GROα, Neutrophil Activating Protein 3 (NAP-3), and Melanoma Growth Stimulating Activity-Alpha (MGSA-α)." (PMID 34833360, 2021). "Originally identified as a melanoma growth stimulatory activity protein, CXCL1 is constitutively highly expressed in melanoma cells and cooperates with oncogenic drivers, or loss of tumor suppressors, to promote tumor development." (PMID 34195201, 2021). "In vitro transwell migration assays demonstrated a strong migration of BM-derived PMN-MDSC from melanoma bearing mice towards a gradient of the CXCL1 concentration." (PMID 33578808, 2021). "The results showed a strong correlation of elevated intratumoral concentrations of CXCL1 with decreased overall survival of melanoma patients." (PMID 33578808, 2021). "We observed that CXCL1 was predominantly produced by the melanoma cells, while IL6 and LIF were expressed mainly by the fibroblasts and CXCL8 by both cell types." (PMID 33182777, 2020). "To further corroborate the reduction of metastatic features of melanoma tumor also in vivo we reported a significant reduction of the pro-metastatic chemokine CXCL1 in the plasma of naproxen-HBTA treated mice as compared with vehicle-treated mice." (PMID 30800067, 2019). "Growth-regulated oncogene α (GRO-α), also called chemokine (C-X-C motif) ligand 1 (CXCL1), is overexpressed in melanoma and is involved in melanoma growth, survival, angiogenesis and metastasis." (PMID 31739477, 2019). "In a similar way, the treatment by gavage with the mixture with omega-3 and omega-6 (1:1 ratio) also altered the cytokines levels in the melanoma microenvironment, since the CXCL1 levels were significantly reduced in this group compared to the control group." (PMID 31374840, 2019). "CXCL1 is also expressed in 70% of human melanomas and it is involved in cellular transformation, tumor growth, homing, and metastasis." (PMID 31920649, 2019). "CXCL1 is an important chemokine whose levels result up-regulated in melanoma and it is essential for the establishment and the maintenance of the tumoral potential of melanoma." (PMID 30800067, 2019). "Our results, demonstrating that CXCL1 serum levels were significantly reduced in B16/PTGS2Δ melanoma bearing mice, are completely in line with these findings and further support the ability of PTGS2 to regulate CXCL1 secretion in melanoma." (PMID 31920649, 2019). "Based on these observations, we analyzed the ratio between the levels of IL-10 and the other cytokines (IL-6 and CXCL1) in the melanoma microenvironment." (PMID 31374840, 2019). "In this study, the B16 melanoma cells produced different levels of CXCL1, CXCL10, M-CSF, and CCL5 compared to the B16/BL6 cells." (PMID 30123429, 2018). "It was reported that CXCL1 is increased in malignant melanoma cells and is involved in the metastasis of malignant melanoma." (PMID 30123429, 2018). "CXCL1 encodeschemokine (C-X-C motif) ligand 1, also known as growth-regulated oncogene α (GRO) or melanoma growth stimulatory activity (MGSA)." (PMID 29662619, 2018). "Presented here analysis demonstrated that melanoma cells secrete different levels CXCL1 and CXCL8 and rather high levels of CXCL2 and CXCL3 chemokines." (PMID 28129639, 2017). "More specifically, reports in gastric cancer and melanoma provide evidence for the direct role of CXCL1 (a CXCR2 ligand) in regulating the protein levels of KRAS." (PMID 26771140, 2016). "While CXCL1 expression is de-regulated in a number of solid tumors, including: melanoma, prostate cancer, bladder cancer, CXCL1 has been shown to play important functional roles in breast tumors." (PMID 26252654, 2015). "Increased expression of CXCL1 has been reported in multiple tumor types including prostate cancer, gastric cancer, renal cell carcinoma and melanoma." (PMID 25344051, 2014).
melanoma (continued). "The down-regulation of HPSE expression using RNA interference resulted in decreased levels of mRNA and protein of IL-8 and chemokine (C-X-C motif) ligand 1 (CXCL1) in the human malignant melanoma cell line A375." (PMID 25295599, 2014). "We have demonstrated here that senescent melanoma cells secrete IL-6, IL-8 [CXCL8] and GRO [CXCL1, 2 and 3] in vitro and in vivo, which are associated with the pro-inflammatory response and recruitment of neutrophils and macrophages to senescent tumour cells." (PMID 23180582, 2013). "Herein, we provided evidence that the knockdown of HPSE with a HPSE miRNA reduced IL8 and CXCL1 in melanoma cells at both the transcriptional and translational levels." (PMID 22719918, 2012). "All of these genes, as well as the more moderately increased CXCL1, have been shown to be important both in neutrophil chemotaxis and in melanoma growth." (PMID 22745913, 2012). "Studies using melanoma tumour models support the role of CXCL1, CXCL2, and CXCL3 in mediating tumour angiogenesis and levels of all three chemokines are highly expressed in melanoma tumours." (PMID 21298036, 2011). "During the progression from normal human melanocytes (n = 1) over melanoma in situ (n = 2) and primary melanoma (n = 14) to metastatic melanoma (n = 41) there is a significant trend of increase of CXCL1 gene expression (p = 0.0237)." (PMID 20030852, 2009). "In murine models of squamous cell carcinoma and Lewis lung cancer CXCL1 expression was shown to parallel tumor growth and in adrenocortical and prostate carcinoma as well as in melanoma CXCL1 was shown to mediate tumorigenicity." (PMID 18578857, 2008). "These chemokines have previously been shown to stimulate melanoma cellular proliferation and CXCL1 and CXCL8 were shown to be involved in invasion and metastasis of melanoma cells." (PMID 17261188, 2007). "Expression of CXCL1 is upregulated relative to healthy tissue in many cancerous tumors such as bladder cancer, colon cancer, gastric cancer, hepatocellular carcinoma, non-small-cell lung carcinoma, melanoma, ovarian cancer, PDAC, and renal cell carcinoma." (PMID 40427171, 2025). "Notably, melanoma cells in dynamic interaction with NHKs exhibited a significant downregulation of bFGF, CXCL-1, CXCL-16, and IL-8 compared to monocultures, possibly since keratinocytes are a primary source of these factors." (PMID 40869222, 2025). "In addition, the modified CXC chemokine receptor 2 (CXCR2) in T cells engaged with CXCL1 in melanoma cells and increased migration of T cells to melanoma tissue." (PMID 39835140, 2024). "Among the downregulated genes known to play an important role in melanoma progression are CXCL1, which exerts melanoma growth-stimulating activity, and MITF, a crucial oncogenic transcription factor to maintain tumor survival, increase proliferation, and promote differentiation." (PMID 39339213, 2024). "CXCL1 expression is higher in malignant melanoma compared to healthy skin." (PMID 38673949, 2024). "Furthermore, CXCL1 displays mitogenic properties, demonstrated on melanoma cells as one of the chemokine’s first identified properties." (PMID 37408240, 2023). "CXCL1 was first described in the 1980s; its first described property was its autocrine stimulation of melanoma cell proliferation, hence its original name: melanoma growth-stimulatory activity (MGSA)." (PMID 37108425, 2023). "As a member of the Chemokines family, CXCL1 acts as an autocrine growth factor in melanoma cells." (PMID 36880057, 2023). "It is therefore relevant to determine the grade of melanoma by measuring the levels of CXCL1 mRNA in melanocytes to determine whether overexpression of CXCL1 in melanocytes can cause tumor formation and metastasis." (PMID 37215082, 2023). "As a result, CXCL1 was initially referred to as melanoma growth-stimulatory activity (MGSA)." (PMID 37408240, 2023).
melanoma (continued). "For example, secreted CXCL1 or CXCL1 overexpression in bladder cancer and melanoma was revealed to be correlated with the enhanced proliferative and metastatic properties of cancer cells, and CXCL1 in vitro was sufficient for cancer cells to generate tumors in a nude mouse xenograft model." (PMID 35764974, 2022). "Furthermore, blocking of CXCR2 in vitro completely abolished the recruitment of PMN-MDSC by CXCL1-secreting Ret melanoma cells." (PMID 33578808, 2021). "Importantly, Ret melanoma cells were found to produce significantly higher amounts of CXCL1 than SVEC4-10 lymphatic endothelial cells." (PMID 33578808, 2021). "One research indicates that primary melanoma cells might down-regulate the invasion activity of metastatic melanoma cells through CXCL1 signaling." (PMID 33767987, 2021). "Taken together, these data support a prominent role of CXCR2/CXCL1 axis in the recruitment of PMN-MDSC in melanoma, indicating this receptor as an ideal target for blocking migration of these cells without impairing the trafficking of tumor-reactive effector immune cells." (PMID 33578808, 2021). "In addition, increased intratumoral levels of CXCL1 significantly correlated with decreased survival of melanoma patients and increased frequencies of PMN-MDSC." (PMID 33578808, 2021). "Considering that melanoma cells can secrete CXCL1, it was mandatory to analyze not only whether the B16F10 cells used in this study could produce this chemokine, but also whether this production could be impaired by fatty acids treatment." (PMID 31374840, 2019). "Besides the evaluation of CXCL1 levels in the melanoma microenvironment, we also analyzed the effect of the fatty acids treatment on in vitro and in vivo levels of IL-6, a pro-inflammatory cytokine, and IL-10, a classical anti-inflammatory cytokine." (PMID 31374840, 2019). "The CXC ligand 1 (CXCL1) chemokine produced by melanoma cells is a major effector of tumor growth." (PMID 31500199, 2019). "In relation to this angiogenic property, it was reported that when CXCL1 produced by melanoma cells binds to CXCR1 or CXCR2 receptors expressed in endothelial cells, it can induce the recruitment of these cells to the tumor microenvironment, leading to the formation of new vessels." (PMID 31374840, 2019). "Amelanotic C-32 melanoma cells produced less CXCL1, CXCL2, and CXCL8 than primary melanocytes." (PMID 30870978, 2019). "In conclusion, our study indicates that primary melanoma cells might down-regulate the invasion activity of metastatic melanoma cells through CXCL1 signaling." (PMID 30123429, 2018). "In the future, the additional establishment of pairs of parent/daughter melanoma cell lines might be necessary to confirm the significance of CXCL1 in the cell-cell interaction of invasion." (PMID 30123429, 2018). "CXCL1 from primary melanoma cells, B16, might inhibit the MMP2 activity of metastatic melanoma cells, B16F10." (PMID 30123429, 2018). "CXCL1 is a protein showing melanoma growth stimulating activity." (PMID 30355311, 2018). "The molecular mechanisms clarified in the present study indicate that the CXCL1 signal might be a beneficial target for the development of a novel therapy against melanoma." (PMID 30123429, 2018). "The production level of CXCL1 differs among human melanoma cell lines." (PMID 30123429, 2018). "For example, the binding of PARP1 to NF-κB could activate the expression of melanoma growth stimulatory activity-regulated protein (CXCL1), subsequently improving the progression of melanoma." (PMID 28991194, 2017). "Indeed, when T-cells were engineered to express CXCR2, their recruitment to B16 murine melanoma overexpressing CXCL1 was increased, resulting in greater tumour regression compared to T-cells lacking CXCR2 overexpression." (PMID 28435677, 2017). "Likewise, a study in melanoma showed that CXCL1-mediated melanocyte transformation involves the induction of RAS expression." (PMID 26771140, 2016).
melanoma (continued). "CXCL1 has been shown to be a growth‐regulated oncogene with melanoma growth‐stimulating activity." (PMID 27682863, 2016). "NFκB is involved in CXCL1 transcription in Hs294T malignant melanoma cells." (PMID 24580964, 2014). "CXCL1 has been shown to be induced in fibroblasts by melanoma cells." (PMID 25344051, 2014). "CXCL1 is highly expressed in melanoma cell lines and promotes malignant melanoma tumor progression." (PMID 24580964, 2014). "NFκB is found to regulate CXCL1 transcription in Hs294T malignant melanoma cells." (PMID 24580964, 2014). "For example, CXCL1 has been reported to be expressed in melanoma, breast, colon and ovarian cancer." (PMID 23665907, 2013). "We wished to understand whether CXCL1 may play a role in melanoma so we analyzed published microarray gene expression data." (PMID 20030852, 2009). "The third ELR+ chemokine under investigation, CXCL1, originally identified as melanoma growth stimulating activity, has recently been adressed a role in HIV-infection and correlated with tumorigenic and angiogenic effects and metastasis in squamous cell carcinoma and melanoma." (PMID 18578857, 2008). "Therefore, the increase in CXCL1 expression in melanoma depends partly on MITF." (PMID 35054978, 2022). "In addition, other experimental studies revealed that adipocytes co-cultured with melanoma cells induce the secretion of chemoattractant factors (CXCL1, CXCL2, and CXCL5) added to a local immune cell recruitment, especially of M2 macrophages, in the “tumour niche”." (PMID 35334544, 2022). "Therefore, the high expression of CXCL1 might promote melanoma cell viability, invasion, and proliferation." (PMID 33767987, 2021). "In addition to melanoma, CXCL1 stimulated pancreatic tumor growth." (PMID 34503058, 2021). "We found that CXCL1 plasma levels of tumor-bearing mice treated with naproxen-HBTA were significantly lower as compared to control mice suggesting a potential effect of this new molecule on the production of chemokines involved in the metastasis spreading of malignant melanoma." (PMID 30800067, 2019). "Previous studies show that CXCL1 mediates glial progenitor cell proliferation during development of the brain but it has also been shown to have a role in the promotion of angiogenesis, oncogenesis in prostate cancer, in melanomas and in increased tumorigenicity of gliomas." (PMID 19558675, 2009). "R.E treatment enhanced pathwaysassociated with immune activation, including upregulation of ISGssuch as IRF1, MX1, and CXCL1, as well as pro-inflammatory cytokinesincluding TNF and IL6 in melanoma cells." (PMID 41341044, 2025). "The membranes exhibit clear upregulation of several chemokines in the melanoma SPNs, including CCL3, members of the GRO family (CXCL1/2/3), and IL-8, all of which are highlighted in red boxes." (PMID 40869222, 2025). "Enrichment of Hsp90/p‐IKKα/β complex in hypoxic melanoma-derived EVs can activate the IKK/IκB/NF‐κB signaling pathway, leading to increased expression of CXCL1 and promoting melanoma angiogenesis and progression." (PMID 40108630, 2025). "FGF-2, CXCL-1, IL-8, and VEGF-A were identified as mediators of the activity of melanoma cells on keratinocyte phenotype." (PMID 39201498, 2024). "Solid‐state antibody chip results, including 105 antibodies, showed that GC‐7 and GL‐1 affected the expression of melanoma cytokines, among which ANG, IGFBP3, CSF2, CD71, CXCL1, and MMP9 were the most significant." (PMID 38952061, 2024). "Using the available Gene Expression Omnibus (GEO) cohort, we evaluated CXCR1, CXCR2, and CXCL1-3, 5 and 8 (CXCR1/CXCR2 ligands) expression in nevi and melanoma." (PMID 37270599, 2023).